KPRP (keratinocyte proline rich protein)
Synonyms: C1orf45
Tractability: No criterion of Open Targets' tractability assessment is met for any kind of drug.
Gene: Protein-coding gene on chromosome 1 (152,758,025 to 152,762,056, forward strand). Ensembl gene ENSG00000203786.
Subcellular location: Cytoplasm
Pathways (Reactome):
Developmental Biology: Differentiation of Keratinocytes in Interfollicular Epidermis in Mammalian Skin
Gene Ontology:
Molecular function: protein binding
Cellular component: extracellular exosome; cytoplasm
Genetic constraint (gnomAD): Loss-of-function variants: 1 observed, 0.64 expected, observed/expected ratio (o/e) 1.55, 90% interval 0.32 to 1.92. That is too few expected variants to judge how well the gene tolerates losing a copy. Missense variants: 820 observed, 784.55 expected, observed/expected ratio (o/e) 1.05, 90% interval 0.99 to 1.11. Synonymous variants: 282 observed, 291.36 expected, observed/expected ratio (o/e) 0.97, 90% interval 0.88 to 1.07.
Homologues: Orthologues: chimpanzee KPRP (99% identical), macaque KPRP (93% identical), guinea pig KPRP (64% identical), mouse Kprp (62% identical), rat Kprp (61% identical), zebrafish ttll6 (11% identical), Drosophila melanogaster TTLL3A (8% identical), Drosophila melanogaster TTLL6B (8% identical), Drosophila melanogaster TTLL3B (7% identical), Drosophila melanogaster TTLL15 (7% identical), Caenorhabditis elegans ttll-15 (6% identical). Paralogues in human: TTLL6 (13% identical), TTLL7 (11% identical), TTLL11 (11% identical), TTLL8 (10% identical), TTLL13 (10% identical), TTLL4 (10% identical), TTLL3 (9% identical), TTLL2 (8% identical), TTLL12 (7% identical), TTLL1 (7% identical), TTLL10 (7% identical), TTLL9 (6% identical).
Diseases named in the same sentence as KPRP in open-access papers:
KPRP is named in the same sentence as 6 diseases in open-access papers, as found by Europe PMC text mining. Sharing a sentence is not in itself a finding about the gene and the disease. The quoted sentences say what the papers report.
adenoma (1 paper, 2016). A neoplasm arising from the epithelium. "Truncating mutations were also validated in SCUBE2, RELN, FBXW7, MLL3, WTX/FAM123B, OTUD7B and KPRP across the MAP and FAP adenomas." (PMID 26414517, 2016).
cancer (2 papers, 2023 to 2025). A tumor composed of atypical neoplastic, often pleomorphic cells that invade other tissues. "The potential contribution of taxifolin to HRNR, FLG2, CRCT1, KPRP and other tumor suppressor gene expressions in BC via its impact on cell metabolism is indeed intriguing, considering that metabolic alterations are a typical feature of cancer cells." (PMID 37370814, 2023).
tumor (2 papers, 2023 to 2025). "Given that these BCs harbor 1q21.3 amplification and the increased copy numbers of HRNR, FLG2, CRCT1 and KPRP genes, these recurrent BCs are likely vulnerable to these genes-derived tumor suppressions." (PMID 37370814, 2023). "Collectively, the evidence suggests that HRNR, CRCT1, KPRP, and FLG2 promote cornification, which might underlie their potential tumor-suppressive action in relation to BC (see Discussion for details)." (PMID 37370814, 2023). "Three genes were established as tumor suppressors and eight were novel to BC, including HNRN, KPRP, CRCT1, and FLG2." (PMID 37370814, 2023). "In addition to possessing tumor-suppression functions, these taxifolin-induced genes (HRNR, FLG2, CRCT1, and KPRP) reside in 1q21.3 and are coamplified in recurrent BCs with 1q21.3 amplification." (PMID 37370814, 2023).
KPRP also shares sentences with these, for which no sentence is quoted: breast carcinoma (1 paper); pancreatic adenocarcinoma (1); pancreatic cancer (1).